TKTL1 (transketolase like 1)
Diseases named in the same sentence as TKTL1 in open-access papers (continued):
Sharing a sentence is not in itself a finding about the gene and the disease.
cancer (continued). "Overexpression of transketolase-like 1 protein TKTL1 in cancer cells has been reported to correlate with enhanced glycolysis and lactic acid production." (PMID 26187043, 2015). "Flow cytometric analysis confirmed Apo10 and TKTL1 labeling in BICR cancer cells as a positive control." (PMID 24304513, 2013). "IHC double staining (representative FFPE OSCC tissue slide) and ICC double staining of BICR56 cancer cells indicates 50–60% TKTL1+ co-expression with Apo10+ in cancer cells." (PMID 24304513, 2013). "Although the importance of TKTL1 in cancer proliferation, survival, and metabolism is well established, several reports have suggested that TKTL1 is incapable of enzymatically functioning as a TKT." (PMID 24280319, 2013). "Single staining of the OSCC cell lines BICR3 and BICR56 in cytospins served as an additional positive control and confirmed the presence of the Apo10 epitope and expression of TKTL1 in cancer cells." (PMID 24304513, 2013). "Inhibition of TKTL1 mRNA translation has been shown to inhibit cancer cell proliferation and to decrease lactate production." (PMID 24304513, 2013). "While a possible biological function of human TKTL2 remains to be discovered, TKTL1 has been suggested to be a critical determinant for energy metabolism, growth and invasion efficiency of malignant tumors." (PMID 23118983, 2012). "Specific inhibition of TKTL1 mRNA has been shown to inhibit cancer cell proliferation in functional studies." (PMID 21854597, 2011). "The significance of TKTL1-activity for both proliferation and glucose metabolism in cancer was recently demonstrated in functional studies using RNA interference." (PMID 19812737, 2008). "Given the novel role of TKTL1 in the metabolism of aggressive cancer cells, as discussed within this article, the pathways of glucose fermentation require a thorough re-evaluation." (PMID 19812737, 2008). "Subsequently, TKTL1 was found to be overexpressed in a wide variety of solid cancers and significantly correlated with aggressiveness in different carcinoma entities." (PMID 19812737, 2008). "In order to determine TKTL1 protein expression levels in human carcinomas, we performed IHC on 1030 human carcinomas derived from 16 different epithelial tumour entities using a monoclonal antibody (JFC12T10) that specifically detects TKTL1." (PMID 16465194, 2006). "Activated Akt was detected in 69% of carcinomas examined, whereas 83% of tested carcinoma specimens showed overexpression of TKTL1." (PMID 16465194, 2006). "Because their function is similar to the role of TKTL1 in different cancer types, it was hypothesized that these genes could be directly or indirectly regulated by TKTL1 during spermatogenesis." (PMID 40680550, 2025). "The data validated the prognostic significance of TKTL1 in certain specific cancer types, wherein the prognostic value of TKTL1 expression varied, depending on the type of cancer in whether it increased or decreased." (PMID 38675412, 2024). "TKTL1 is an enzyme participating in cancer glycolytic metabolism." (PMID 36781976, 2023). "The lower levels of TKTL1 were found in cancer tissues than adjutant in the TCGA database." (PMID 35711845, 2022). "Since TKTL1 has a cancer-promoting biological activity, this paper aims to explore whether TKTL1 can participate in the malignant process of CC cells through the glucose metabolism pathway." (PMID 34922556, 2021). "Moreover, compared with corresponding adjacent non-cancer tissues, relative TKTL1 levels in ccRCC tissues were nearly 3 times higher, consistent with the almost doubled R5P levels." (PMID 31175280, 2019). "TKTL1-overexpressing cancer cells exhibit elevated ribose-5-phosphate levels." (PMID 31175280, 2019). "Indeed, TKTL1 is overexpressed in various cancers and is correlated with poor prognosis in colon, urothelial, gastric, and lung cancers as well as in ocular adnexa carcinomas, rectum carcinomas, and laryngeal squamous cell carcinomas." (PMID 31175280, 2019).
cancer (continued). "Recently, a third metabolic pathway was discovered in cancer cells by which glucose can be metabolized, the TKTL1 pathway, which converts X5P (an intermediate of PPP) to glyceraldehyde 3-phosphate and a two-carbon metabolite, likely acetate, which can be further metabolized to cytosolic AcCoA20,21." (PMID 29657327, 2018). "Furthermore, TKTL1 has been extensively investigated in cancers, and it has been supposed to be a catalytically active mutant form of human TKT, through formation of heterodimers with other TKT isoforms and/or by activation of other thiamine derivatives." (PMID 28143530, 2017). "Thus, TKTL1 drives the glucose metabolism and contributes to the Warburg effect in cancer cells through its transketolase activity." (PMID 27391434, 2016). "Second, TKTL1 affects glutamine metabolism, the other main carbon source in cancer cells." (PMID 27391434, 2016). "However, little is known about how TKTL1 participates in all these processes that guarantee the growth and survival of cancer cells." (PMID 27391434, 2016). "Furthermore, several cancer cell lines have been reported to be positive for TKTL1 protein upon Western blot analysis, cyto-immunohistochemistry and RT-qPCR." (PMID 26187043, 2015). "Similarly, immunohistochemistry analyses presented here support a rather rare expression of TKTL1 protein in cancer and normal cell lines." (PMID 26187043, 2015). "However, the pathway is also significant in cancer cell metabolism, through the Warburg effect and the overexpression of a mutant form of the human transketolase (TKTL1) in various cancer cell lines." (PMID 23776642, 2013). "However, the lack of activity of purified TKTΔ38 in solution contradicts reports describing the TKT activity of TKTL1 when exogenously overexpressed or repressed in cancer cells." (PMID 24280319, 2013). "It has been hypothesized that TKTL1 could exhibit enzymatic activity that allows ATP synthesis in hypoxic and cancer cells in a pathway analogous to the phosphoketolase pathway present in some heterofermentative bacteria." (PMID 23118983, 2012). "TKTL1, an altered isoform of the transketolase gene, is upregulated in many human cancers." (PMID 21854597, 2011). "The expression of TKTL1 has been detected and correlated with several kinds of cancer so far." (PMID 21980427, 2011). "The discovery of the transketolase-like 1 (TKTL1) enzyme in aggressive cancers may deliver a missing link in the interpretation of the Warburg effect." (PMID 19812737, 2008). "The identification of TKTL1, which participates in glucose metabolism in cancer cells, sheds a new light on this pathway, as TKTL1 represents an enzyme with transketolase activity and a potentially elevated substrate spectrum with altered reaction characteristics." (PMID 19812737, 2008). "It remains to be determined whether the enzymatic activity of TKTL1 contributes to glucose-induced lipogenesis, loss of OXPHOS, and the formation of lactate in aggressive cancer cells." (PMID 19812737, 2008). "TKTL1-activity could be the basis for a rapid fermentation of glucose in aggressive carcinoma cells via the pentose phosphate pathway, which leads to matrix acidification, invasive growth, and ultimately metastasis." (PMID 19812737, 2008). "The determination of TKTL1 expression in human malignancies may help to identify cancer patients that would benefit from an anti-transketolase cancer therapy." (PMID 16465194, 2006). "The only transketolase gene overexpressed in carcinoma tissue was the TKTL1 gene." (PMID 16465194, 2006). "In addition, the overexpression of TKTL1 in several human cancers may lead to the transformation of substrates necessary for glucose degradation (in the glycolysis pathway)." (PMID 40680550, 2025). "Moreover, TKTL1 has been shown to have connections with various cancers." (PMID 38675412, 2024).
cancer (continued). "Moreover, to confirm the metabolic effects of pioglitazone we investigated key proteins indicative of altered glucose metabolism in cancer cells, such as the transporters Glut-1 and SLC15A (Solute-linked carrier family A1 member 5), G6PD (glucose-6-phosphate dehydrogenase) and TKTL1 (Transketolase)." (PMID 31027492, 2019). "In conclusion, we provide unprecedented evidence that TKTL1 confers a growth advantage to proliferating cells and is essential in cancer metabolic reprogramming, suggesting that TKTL1 might be a promising target for the design of future anti-cancer therapies." (PMID 27391434, 2016). "Thus, the TKTL1-driven metabolic adaptation may promote cancer progression through a variety of mechanisms." (PMID 26907172, 2016). "However, the presumed key role of TKTL1 in cancer cell metabolism has been put into question in numerous recent studies, where no overexpression of TKTL1 could be detected in several malignant tumor cell lines." (PMID 23118983, 2012). "We could show an expression of TKTL-1 in ACC as well as in some other malignant tumors." (PMID 19545368, 2009). "Besides a positive correlation of TKTL1-expression, aerobic glycolysis, and the aggressiveness of different cancer types, targeted knockdown of TKTL1 in vitro already demonstrated its functional relevance for both growth and metabolism of cancer cells." (PMID 19812737, 2008). "We propose, that TKTL1 mediates aerobic glycolysis, which prevents hyperglycaemic damage as well as the formation of ROS, and which may be a prerequisite for rapid cell growth as observed in both male germ cells and cancer." (PMID 19812737, 2008). "Proliferation-influencing activities of TKTL1 might play a role in a variety of cancers." (PMID 18700018, 2008). "The utilization of flow cytometry to detect Apo10 and TKTL1 in blood macrophages (epitope detection in macrophages, EDIM) is a new method for diagnosing noninvasive cancer." (PMID 39644404, 2025). "Transketolase-like-1 (TKTL1), one of the three isoforms of TKT, is involved in the regulation of multiple cancer-related events." (PMID 39859324, 2025). "Being an enzyme that is important for cell biosynthesis, TKT, as well as both the TKTL1 and TKTL2 isoenzymes, have turned out to be important prognostic markers and potential regulatory targets in various cancer types." (PMID 41302487, 2025). "This CDH1‐VHL‐HIF1α/AARS2‐R5P/TKTL1 circuit is supported by the observation that low R5P levels and high CDH1 expression correlate with proliferating cancer cells and tissues." (PMID 41020695, 2025). "Since TKTL1 represents a drugable target, the EDIM based detection of TKTL1 enables a targeted cancer therapy using the vitamin derivatives oxythiamine or benfo-oxythiamine." (PMID 28425973, 2017). "Thus, TKTL1 may link the synthesis of nucleotide precursors (R5P) to the production of fatty acid precursors (AcCoA), providing an alternative explanation for how cancer cells can generate new lipids when AcCoA production from glucose metabolism is restricted." (PMID 27391434, 2016). "Some recent evidences suggest that DNA damage induced by adriamycin enhances the TIGAR and TKTL1 expression and knocking down the TKTL1 or WRN complex both leads to reduced glycolytic metabolism and accumulation of DNA damage in cancer cells." (PMID 25925410, 2015). "Summarizing in other words, targeting detoxifying systems (e.g. TKTL1, LDHA) make cancer cells or (oral) precursor lesions more vulnerable to apoptosis." (PMID 25048361, 2014). "In comparison to normal tissue and hyperplasia a significantly (p < 0.05) increased expression of IGF-R1β, GLUT-1, HK 2, TKTL1, LDHA, SDHA, SDHB, and ATP synthase was observed in cancer cells of OSCC." (PMID 25048361, 2014). "This is supported by our data showing a significantly correlation of proliferating cancer cells with both glycolysis-related proteins (GLUT-1, TKTL1), and OXPHOS-related enzymes (SDHA, SDHB, ATP synthase)." (PMID 25048361, 2014).
cancer (continued). "For investigation of proliferating cancer cells and its relation to metabolic characteristics, we performed correlation analysis of Ki-67 with GLUT-1, HK 2, LDHA, TKTL1, SDHA, SDHB, and ATP synthase in OSCC." (PMID 25048361, 2014). "The detection of the Transketolase-like-1 (TKTL1) protein and its role in the pentose phosphate pathway (PPP) first described a link between enhanced glycolysis and cancer." (PMID 21854597, 2011). "Notably, Apo10, TKTL1, and Apo10 + TKTL1 (APT) levels were significantly greater in the cancer group than in the control group (P < 0.001), demonstrating high diagnostic value (AUC = 0.901, 0.871, 0.938) that surpassed CA-125, CA-199, CA-153, and CEA." (PMID 39644404, 2025). "TKTL1 is an enzyme involved in the nonoxidative pentose‐phosphate pathway that was reported to be overexpressed in several human cancers." (PMID 36017582, 2022). "The specific detection of TKTL1 protein in paraffin sections with JFC12T10 allowed the discrimination between healthy TKTL1-negative epithelium and TKTL1-positive carcinoma cells." (PMID 26187043, 2015). "In this context glycolysis-related proteins may act as detoxifying system (LDHA, TKTL1) of increased ATP producing (and ROS generating) OXPHOS-related proliferating cancer cells." (PMID 25048361, 2014). "Consistent with the proposed role of TKTL1 in energy generation during the cell cycle, Warburg already described that aerobic glycolysis is not restricted to cancer, but also occurs in healthy tissues like e.g. testis and retina." (PMID 19812737, 2008). "As TKTL1-TKT heterodimer formation is required for accumulating R5P and accelerated cell proliferation, methods of interfering with TKTL1-TKT heterodimer formation to decrease R5P accumulation and inhibit DNA synthesis should be further explored to contain diseases such as cancer." (PMID 31175280, 2019).
neurodegenerative disease (1 paper, 2008). A disorder of the central nervous system characterized by gradual and progressive loss of neural tissue and neurologic function. "Thereby, TKTL1 may prevent the formation of toxic glucose adducts (advanced glycation end products, AGE), which are frequently seen in diabetic lesions and neurodegenerative diseases." (PMID 19812737, 2008).
TKTL1 also shares sentences with these, for which no sentence is quoted: adenocarcinoma (2 papers); squamous cell carcinoma (2); bacterial vaginosis (1); benign tumors (1); chronic myeloid leukemia (1); clear cell renal cell carcinoma (1); conjunctival melanoma (1); esophageal squamous cell carcinoma (1); follicular thyroid carcinomas (1); granulosa cell tumor (1); granulosa cell tumors of the ovary (1); invasive carcinoma (1); laryngeal squamous cell carcinoma (1); liver cancer (1); lung adenocarcinoma (1); lymphoma (1); metabolic syndrome (1); Obesity (1); pancreatic cancer (1); pancreatic ductal adenocarcinoma (1); papillary carcinoma (1); sarcoma (1); type 2 diabetes (1); urothelial carcinoma (1).